DNM2 (dynamin 2)
Diseases named in the same sentence as DNM2 in open-access papers (continued):
Sharing a sentence is not in itself a finding about the gene and the disease.
congenital myopathy (13 papers, 2014 to 2026). "Type 1 myofiber predominance is also observed in other triadopathies, including RYR1, DNM2, BIN1 and MTM1-associated congenital myopathies." (PMID 39209426, 2024). "Seven patients had congenital muscular dystrophies: LAMA2-related dystrophy (n = 5), COL6-related dystrophies (n = 1) or α-dystroglycanopathy (n = 1), and three patients had congenital myopathies: DNM2-related myopathy (n = 1) and TTN-related myopathy (n = 2)." (PMID 32028919, 2020). "This first pharmacological validation of DNM2 as a therapeutic target through ASO-mediated knockdown provides an attractive therapeutic strategy that may be applied to patients with this severe congenital myopathy." (PMID 28589938, 2017). "Here we focus on the ubiquitously expressed dynamin 2 (DNM2) and characterize the skeletal muscle-specific function of its different isoforms and their modulation as a therapeutic target in a congenital myopathy." (PMID 36369230, 2022).
glioma (12 papers, 2013 to 2025). A benign or malignant brain and spinal cord tumor that arises from glial cells (astrocytes, oligodendrocytes, ependymal cells). "Some reports indicate that DNM2 stimulates migration and invasion of cancer cells, including glioma cells." (PMID 34831480, 2021). "In brain cancer, dynamin 2 is a downstream effector of the PDGFRα-PI3K/SHP-2 signalling in glioma cells and mediates PDGFRα -SHP-2-promoted glioblastoma growth and invasion." (PMID 28402939, 2017). "Dynamin-1 can compensate the dynamin-2 inhibition as dynamin-1 is known being typically expressed in neurons, neuroendocrins cells and also in glioma cells." (PMID 24386117, 2013). "Importantly, we showed that inhibition of DNM2 or LRP-1 also decreased glioma cell responsiveness to gefitinib during cell evasion from tumour spheroids." (PMID 34831480, 2021). "Importantly, inhibiting endocytosis by targeting DNM2 or LRP-1 protects glioma cells against gefitinib treatment during cell dissemination from tumour spheroids." (PMID 34831480, 2021). "Depletion of endogenous dynamin 2 by short hairpin RNAs (shRNAs) inhibited PDGFRα-stimulated phosphorylation and activation of Akt, extracellular signal-regulated kinase 1/2, Rac1 and Cdc42, prevented glioma cell migration and tumor growth as well as invasion in the brains of mice." (PMID 28402939, 2017). "Possibly, early-stage gliomas upregulate DNM1 to support synaptic-like vesicle recycling, then transition to DNM2-mediated uptake in intermediate stages." (PMID 40705199, 2025).
neuropathy (12 papers, 2008 to 2026). A disorder affecting the nervous system that manifests with pain, tingling, numbness, and/or muscle weakness. "This paradox, in which efforts to compensate for a loss-of-function neuropathy risk inducing a gain-of-function myopathy, highlights the need for tightly controlled modulation of DNM2 activity in future therapeutic strategies." (PMID 41683892, 2026). "In this study, we have analysed mice carrying the equivalent Dnm2 K562E mutation that causes dominantly inherited CMTDIB neuropathy in humans." (PMID 32129442, 2020). "In summary, we have shown that mice with the corresponding mutation to the CMTDIB neuropathy-causing DNM2 K562E allele show hallmarks of a primary myopathy." (PMID 32129442, 2020). "Why do Dnm2 wt/K562E mice fail to show overt signs of a neuropathy, despite genetically mirroring the DNM2 WT/K562E mutation found in CMTDIB?" (PMID 32129442, 2020). "The intimate dependency of SCs on DNM2 is consistent with a particular susceptibility of these cells to neuropathy-associated DNM2 mutations." (PMID 30648534, 2019). "Induced loss of DNM2 specifically in adult SCs evoked an acute and robust demyelination, accompanied by clinical neuropathy and coupled with SC dedifferentiation and invasion of inflammatory cells." (PMID 30648534, 2019). "With regard to disease mechanisms of neuropathy-causing dominantly inherited DNM2 mutations, generation and careful analysis of animal models carrying such mutations are required." (PMID 30648534, 2019). "Schwann cell-specific ablation of dynamin 2 in adult mice causes a transient neuropathy." (PMID 30648534, 2019). "Furthermore, an impact of DNM2-mediated internalization on surface receptors (potentially also altering signaling) is indirectly supported by studies in cell culture, showing that expression of a neuropathy-associated DNM2 mutant alters surface levels of integrin β1 and ErbB2." (PMID 30648534, 2019). "Thus, we wondered whether also all other functions of SC-DNM2 that are required to maintain myelinated nerves can be preserved by the Dnm2 K562E allele, keeping in mind that even induced loss of DNM2 in SCs of adult mice causes a strong (transient) neuropathy-like phenotype." (PMID 32129442, 2020). "These clinical features are in contrast with the presentation observed in patients with DNM2-associated HSP described here, although some overlap with CMT2 neuropathy exists, especially late in the disease." (PMID 26517984, 2015). "Since the DNM2 K562E mutation in humans leads to an intermediate neuropathy with loss of large-diameter axons, a characteristic feature of axonal CMT too, we next assessed whether Dnm2 K562E mice develop signs of an axonal phenotype." (PMID 32129442, 2020). "However, we found also that the P0Cre Dnm2 fl/K562E animals develop a striking neuropathy-like phenotype between 3 and 4 weeks of age." (PMID 32129442, 2020). "The lack of a neuropathy in our Dnm2 wt/K562E mouse model, however, appears to have enabled the fortuitous detection of an otherwise potentially hidden primary myopathy, since an overt neuropathy would have been most likely associated with an overshadowing secondary muscular atrophy." (PMID 32129442, 2020). "Taken together, our results indicate a mild but definitive and enduring myopathy-like phenotype in Dnm2 wt/K562E mice, which develops in the absence of a detectable neuropathy." (PMID 32129442, 2020). "Strikingly, when Dnm2 was deleted in adult SCs, non-recombined SCs still expressing DNM2 were able to remyelinate fast and efficiently, accompanied by neuropathy remission." (PMID 30648534, 2019).
prostate carcinoma (11 papers, 2014 to 2025). A carcinoma that arises from epithelial cells of the prostate gland. "A third study in which prostate cancer cells were injected in prostate of mice showed that tumor weight and lymph node metastases are reduced when DNM2 is inhibited by RNA interference in the injected cells." (PMID 34294140, 2021). "Additionally, high expression of DNM2 has been reported in a series of cancer types, including cervical, pancreatic, and prostate cancers." (PMID 39610009, 2024). "Similarly, the DNM2-dependent endocytosis of the Interleukin 24 (IL-24) with its receptor is required in prostate cancer cells for the tumor suppressor action of the IL-24 (also called MDA-7)." (PMID 34294140, 2021).
Alzheimer disease (10 papers, 2013 to 2025). A progressive, neurodegenerative disease characterized by loss of function and death of nerve cells in several areas of the brain leading to loss of cognitive function such as memory and language. "More recently, the DNM2 gene has been described as a susceptibility gene for late onset Alzheimer disease, and the DNM2 mRNA levels are decreased in the brains of these patients 28,29." (PMID 25092467, 2014). "Dynamin-2 dysfunction can participate in Alzheimer’s disease development by impairing endocytosis of ß amyloid, resulting in its cellular accumulation." (PMID 29109409, 2017).
cardiomyopathy (10 papers, 2016 to 2025). A disease of the heart muscle or myocardium proper. "The patient was a heterozygous carrier of VUS in DNA methyltransferase 1 (DNMT1) gene (c.1043C> T), and VRK serine/threonine kinase 1 (VRK1) gene (c.8G>A), in addition to dynamin 2 (DNM2) gene (c.2576_2578delCCA), which is associated with severe cardiomyopathies." (PMID 33567613, 2021). "SPEG may have fiber type–specific and tissue-specific roles, which may affect the efficacy of DNM2 reduction in rescuing Speg-related myopathy and cardiomyopathy phenotypes." (PMID 35763354, 2022). "CNM with cardiomyopathy is linked to SPEG and DNM2 mutations, but, in many cases, the genetic cause is unknown." (PMID 26935107, 2016).
glioblastoma (9 papers, 2012 to 2025). The most malignant astrocytic tumor (WHO grade IV). "Like for glioblastoma, importance of phosphorylation of DNM2, at known Src phosphorylation sites, was also demonstrated in migration of pancreatic cancer cell line as overexpression of a phospho-deficient DNM2 mutant is inefficient to promote lamellipodia formation and motile phenotype." (PMID 34294140, 2021). "Important for our studies, PDGFRα activation affects both dynamin-2 that interacts with activated PDGFRα at the advancing edges of motile glioblastoma cells and cortical actin cytoskeleton leading to marked membrane ruffling." (PMID 23028311, 2012). "DNM2 mediates the Platelet Derived Growth Factor Receptor α (PDGFRα)-stimulated growth and invasion of glioblastoma cells through the formation of a Src-phosphorylated DNM2-PDGFRα-tyrosine-protein phosphatase non-receptor type 11 (SHP2) complex." (PMID 34294140, 2021). "Furthermore, DNM2 is not a good prognosis marker for glioblastoma patient survival (TCGA database)." (PMID 32642662, 2019).
pancreatic cancer (9 papers, 2013 to 2025). "Inhibition of DNM2 by overexpressing phospho-deficient mutant in the injected pancreatic cancer cells drastically reduces the number of large tumors outside the injection site." (PMID 34294140, 2021). "In pancreatic adenocarcinoma cell lines, the invasive phenotype was associated to the interaction between DNM2 and Vav1, a Rac1 guanine exchange factor abnormally expressed in pancreatic cancer." (PMID 34294140, 2021). "In pancreatic cancer cells, lipid synthesis potentiates expression of macropinocytosis-associated genes, including SDC1, DNM2, via the ZIP4 (solute carrier family 39 member 4) pathway." (PMID 40408281, 2025). "Orthotopic injection of cells overexpressing DNM2 promotes tumor cells dissemination distal from the injection area compared to mice injected with pancreatic cancer cells with basal DNM2 expression." (PMID 34294140, 2021). "More recently, in pancreatic tumor cells, dynamin 2 was found to promote lamellipodia formation and pancreatic tumor cell migration by its direct binding with Vav1 to promote Rac1 activation and migration." (PMID 28402939, 2017). "In addition to this DNM2 impact on actin cytoskeleton, its impact on microtubule cytoskeleton was demonstrated for migration of pancreatic cancer cells." (PMID 34294140, 2021). "Different cell factors are demonstrated to be involved in the regulation of dynamin 2 function, for example, dynamin 2 is regulated by proto-oncogenic expression of K-RAS in human colon cancer cells and promotes pancreatic cancer cell migration through activation of Rac1." (PMID 28402939, 2017). "Finally, a regulation of DNM2 expression by CD9, a member of the tetraspanin family playing important functions in signal transductions from the plasma membrane, was demonstrated in pancreatic cancer cell lines." (PMID 34294140, 2021).
viral infection (9 papers, 2015 to 2025). "The data demonstrated that Dnm1, Dnm2, and Dnm3 had significant effects on virus infection in shrimp." (PMID 27029712, 2016). "In summary, our study demonstrated for the first time that the entry of PCV3 into PK15 cells involves a clathrin- and dynamin-2-mediated endocytic pathway, where early and late endosomal trafficking, as well as an acidic environment, are essential for viral infection." (PMID 33679671, 2021). "Overexpression of dynamin-2 prior to viral infection led to a statistically significant increase in CXCL10 and CXCL8, while downregulating dynamin-2 led to statistically significant reductions in CCL2, CCL5, CXCL1, CXCL11, IL-1ra, IL-6, MIF, and Serpin E1." (PMID 34683878, 2021). "Our results revealed that before viral infection, inhibition of AnxA2 by A2ti-1 inhibitor suppressed ARV-modulated upregulation of the phosphorylation of Src, p38 MAPK, and caveolin-1 at Y14, as well as the expression levels of dynamin 2, at the 15- and 30-min time points." (PMID 37097149, 2023). "Given that Dnm1, Dnm2, and Dnm3 could be involved in virus infection at the mRNA level, we further hypothesized whether or not recombined Dnm1, Dnm2, and Dnm3 proteins affect the WSSV copies in shrimp." (PMID 27029712, 2016).
hepatocellular carcinoma (8 papers, 2020 to 2025). A malignant tumor that arises from hepatocytes. "The importance to preserve DNM2 expression is also highlighted by the reported analysis of 131 hepatocellular carcinoma showing that patients with low DNM2 expression displayed a significantly worse overall survival." (PMID 34294140, 2021).
leukemia (8 papers, 2016 to 2025). A malignant (clonal) hematologic disorder, involving hematopoietic stem cells and characterized by the presence of primitive or atypical myeloid or lymphoid cells in the bone marrow and the blood. "High DNM2 expression is associated with some clinical and laboratory features, inferior outcomes and with leukaemia cell proliferation." (PMID 27885263, 2016). "In agreement with this, DNM2 mutations co-occur with additional activating alterations in the IL-7 signaling pathway, suggesting a cooperation between these genetic alterations in leukemia development." (PMID 34066732, 2021). "DNM2 expression is increased in ALL, especially in B-ALL in which overexpression is associated with leukaemia cell proliferation and a poor prognosis." (PMID 34294140, 2021). "Interestingly, it was previously shown that mutations in the gene for dynamin II (DNM2), are frequent in ALL patients, hence providing support for a role of dynamin-dependent mechanisms in leukemia development." (PMID 34492077, 2021). "Overexpression of Ikaros in both types of leukemia resulted in reduced transcription of DNM2." (PMID 32085659, 2020). "Our current study suggests that Ikaros suppresses transcription of DNM2 in leukemia cells." (PMID 27885263, 2016). "Importantly, we observed DNM2-inhibitors suppresses proliferation of leukemia cells and is synergistic with CK2-inhibitors." (PMID 27885263, 2016). "We used the WST-1 cell proliferation assay to test whether targeting DNM2, with MiTMAB, a DNM2-inhibitor, had an anti-leukemia effect in ALL cells." (PMID 27885263, 2016). "Inhibiting DNM2 suppresses proliferation of leukemia cells and synergizes with CK2 inhibition." (PMID 27885263, 2016). "An increase in endocytosis following DNM2 overexpression may also help cancer cells to protect themselves to complement-dependent necrotic cell death as suggested by the DNM2-dependent internalization of complement complexes from the plasma membrane in leukemia cells." (PMID 34294140, 2021). "Ikaros directly suppresses DNM2 expression in ALL cells and a CK2-inhibitor which restores Ikaros function and suppresses DNM2 expression in an Ikaros-dependent manner in leukemia cells by recruiting the repressive histone marker-H3K9me3." (PMID 27885263, 2016).
ovarian carcinoma (8 papers, 2013 to 2025). A malignant neoplasm originating from the surface ovarian epithelium. "Moreover, miR-199 encoded by the antisense strand of DNM2, decreased HIF1α and HIF2α expression leading to the reduction of cell migration and invasion, thus establishing the connection between hypoxia and endocytosis in ovarian cancer." (PMID 33240194, 2020). "A recent study showed that DNM2 along with miR-99a (that derived from the opposite strand of DNM2) reciprocally regulate HIFs and ovarian cancer metastasis, suggesting a tumor-suppressive role of DNM2." (PMID 25301729, 2014). "In addition, it was shown in ovarian cancer cell lines that DNM2 levels are transcriptionally down-regulated by the hypoxia-induced factor 1 (HIF-1) which directly binds to the DNM2 promoter." (PMID 34294140, 2021). "Moreover, DNM2 gene derived miR-199 play roles in ovarian cancer metastasis by the regulation of hypoxia induced factors HIF1 and HIF2." (PMID 33240194, 2020). "In epithelial ovarian cancer cells, HIF1α and HIF2α are reciprocally regulated by DNM2." (PMID 33240194, 2020).
melanoma (7 papers, 2010 to 2025). A malignant, usually aggressive tumor composed of atypical, neoplastic melanocytes. "For example in melanoma cells, DNM2 regulates plasma membrane content of the Fas receptor which plays an important role in programmed cell death when bound to Fas ligand." (PMID 34294140, 2021). "Moreover, endogenous depletion of miR-638 but not of DNM2 significantly attenuated the proliferation of melanoma cells." (PMID 25650662, 2015). "DNM2 knockdown did not exhibit any inhibitory effect on migration of melanoma cells." (PMID 25650662, 2015).